BRAF (B-Raf proto-oncogene, serine/threonine kinase)
Diseases named in the same sentence as BRAF in open-access papers (continued):
Sharing a sentence is not in itself a finding about the gene and the disease.
tumor (continued). "Tumors from 870 patients were grouped according to BRAF,RAS,NF1 mutation or triple‐wild‐type status and correlated with tumor and patient characteristics." (PMID 28267273, 2017). "Gain-of-function missense mutations in KRAS and BRAF genes are mutually exclusive CRC drivers and have similar but subtly different roles during initiation and tumor development." (PMID 29167573, 2017). "Despite a previous conception that KRAS and BRAF mutations are mutually exclusive, we found 1 dual BRAFV600E+KRASA164V^submutated tumor that, in our case, was associated with poor prognostic features." (PMID 28178681, 2017). "The reduced ERK activity in BRAF inhibitor‐treated tumours correlated with increased MITF and EDN1 expression." (PMID 28606996, 2017). "Mutant BRAF not only promotes melanocyte proliferation but has also been shown to manipulate the tumor microenvironment by increasing the release of IL-6, IL-10 and VEGF." (PMID 29100459, 2017). "We further demonstrated that this pathology-determined OS can be affected by both tumor stage and status of oncogenic mutations in EGFR, KRAS, ALK, RET, and BRAF genes." (PMID 29137260, 2017). "Positive nuclear RBM3 expression was significantly more frequent in tumours located in the rectum, in BRAF wildtype tumours and in metachronous disease." (PMID 28800641, 2017). "This pathology-defined prognosis is also dependent on both tumor stage and the status of genetic mutations in the EGFR, KRAS, ALK, RET, and BRAF genes." (PMID 29137260, 2017). "The combination of BQ788 with BRAF inhibitor led to a significant reduction in tumour growth, which correlated with strong suppression of DUSP6 expression." (PMID 28606996, 2017). "This tumor was also investigated for KRAS, NRAS, BRAF, and PIK3CA mutations, and a mutation in KRAS exon 4 was found, namely the c.351A>C, p.Lys117Asn." (PMID 29072370, 2017). "For patients whose tumors express an oncogenic BRAFV600E/K mutation, treatment with the BRAF inhibitor vemurafenib (or, in more recent practice, a combination of the BRAF inhibitor dabrafenib and MEK inhibitor trametinib) results in dramatic tumor regression." (PMID 29175850, 2017). "To assess the efficacy of targeting EDNRB signalling, we treated mice bearing A375 tumours either with BRAF inhibitor alone or a BRAF inhibitor/bosentan combination and found that growth was significantly reduced with the combination treatment." (PMID 28606996, 2017). "Although the final Jass classification is divided into five groups, he suggested that that CIMP-High CRC was generally associated with BRAF mutations, KRAS wild type, a right colon tumour, female predominance and MSI-H." (PMID 28097409, 2017). "Tumours that had resumed growth on BRAF inhibitor alone displayed a strong increase in AXL mRNA expression." (PMID 28606996, 2017). "The same research group reported in vitro and ex vivo data showing that autophagy inhibition was able to improve the response to BRAF inhibition in resistant tumour cells." (PMID 29225688, 2017). "A similar effect was observed with A375 ex vivo cultures isolated from tumours that had regressed on BRAF inhibitor (Fig EV3D), as well as with in vitro generated A375‐T cells (Fig EV3E)." (PMID 28606996, 2017). "A multivariate COX proportional hazards model showed that after controlling for CEA, tumor localization and age, BRAF-mutant status is a independent prognostic value (p = 0.002, HR = 7.33, 95% CI [1.04–2.89])." (PMID 28187169, 2017). "All four cases of BRAF-mutated, MLH1-unmethylated tumor histologically showed perineural invasion and tumor budding-positivity." (PMID 26883113, 2016). "In an extension phase of this trial, 32 patients with previously treated BRAF V600E-mutant MM demonstrated a tumor response rate of 81% (n = 26), with two patients demonstrating a CR." (PMID 26767073, 2016).
tumor (continued). "The approach illustrated that, on average, pretreatment tumors harboring a BRAF mutation have higher signals for distinct CD8+ T cells and Th1 cell signatures, signifying a tumor-killing environment." (PMID 27377892, 2016). "In this study, we report a preclinical strategy to assess tumor sensitivity to BRAF and MEK inhibitors, in vivo using PDX models, and ex vivo using histocultures derived from PDXs." (PMID 26909610, 2016). "BRAF and TERT promoter mutations were each significantly associated with high-risk clinicopathological features of PTC, such as old patient age, large tumor size, extrathyroidal invasion, capsular invasion, and advanced disease stages." (PMID 26943032, 2016). "Multiregion analysis was performed in 60 spatially separated tumor areas according to the pathological tumor node metastasis (pTNM) staging and KRAS, NRAS and BRAF mutations were tested using pyrosequencing." (PMID 27916952, 2016). "Accordingly, we show that resistant cells remain sensitive, albeit weakly, to BPTES, but more importantly that BPTES enhances the anti‐tumor activity of BRAF inhibition, presumably by suppressing switching to glutamine metabolism." (PMID 26365896, 2016). "There exists an urgent requirement not only for novel single-agent therapeutics but also combination treatments, as tumours rapidly evolve drug resistance to existing therapies, e.g. BRAF (V600) inhibition and RAF/EGFR or RAF/MEK inhibitor co-treatments." (PMID 27531891, 2016). "Tissue immunostaining showed that six of eight metastatic samples obtained during treatment contained CCL2-positive tumor cells, whereas all samples were stained positive for BRAFV600E and contained the mutated BRAF gene, as shown by sequence analysis." (PMID 26684239, 2016). "WX-554 has demonstrated marked inhibition of ERK1/2 phosphorylation in HT29 cells, and growth inhibition in a range of cell lines in vitro, and tumour growth delay or stasis in vivo, with increased sensitivity in BRAF or RAS mutant cells and tumours." (PMID 27837257, 2016). "The hotspot mutations detected in neoplasms, such as IDH or BRAF mutations, are located at specific genetic loci leading to gains-of-function." (PMID 27529619, 2016). "This is even more important because the application of BRAF-inhibitors in BRAF wild-type patients can lead to a paradoxical MAP-kinase pathway activation resulting in an accelerated tumor growth and worse prognosis." (PMID 27150060, 2016). "Oncogenic RAS and BRAF that potently stimulate ERK signalling drive neoplasia of cutaneous melanocytes in zebrafish and are commonly mutated in human CM, but mutations are vanishingly rare in UM." (PMID 27166257, 2016). "They obtained a 100% sensitivity and specificity but they considered that the VE1 antibody was positive for BRAF V600E only when strong immunostaining (3+) was observed in at least 80% of tumor cells." (PMID 27863476, 2016). "This was correlated with MITF target gene expression and tumor growth, where the BRAF inhibitor/nelfinavir combination led to an over 80% reduction in tumor volume." (PMID 26977879, 2016). "If on one hand it causes resistance to TK-inhibitors, on the other it sensitizes the tumor to BRAF inhibitors." (PMID 27097112, 2016). "This phenomenon of rapid decrease in the concentration of BRAF V600mut ctDNA has been reported before and has been attributed to the destruction of tumor cells and a subsequent rapid clearance of ctDNA." (PMID 27095081, 2016). "Objective responses occurred more frequently in patients with RAS WT (59%) vs RAS MT (41%) mCRC, and in patients with RAS WT/BRAF WT (68%) vs RAS or BRAF MT (37%) tumours." (PMID 27764839, 2016). "In wild-type BRAF patients, the BRAF mRNA expression count was higher in cases with a tumor size > 2 cm." (PMID 27410688, 2016).
tumor (continued). "For mutational profiling, KRAS, BRAF, and PIK3CA hotspot mutations were analyzed in CTCs and ctDNA from 23 samples, nine matched liver metastases and three primary tumor samples." (PMID 27863403, 2016). "Here, we present a retrospective analysis of this first-line trial of panitumumab plus FOLFIRI, reporting efficacy and safety data for first-line FOLFIRI plus panitumumab according to tumour RAS/BRAF status and AREG levels in patients with mCRC." (PMID 27764839, 2016). "In contrast to previous studies, both Japanese and US-CRC cases had a wide range of non-V600E mutations inside and outside the kinase domain including D594G, a kinase-dead BRAF that can drive tumor progression through interactions with CRAF." (PMID 28007036, 2016). "To investigate the molecular mechanisms controlling tumor growth effects of BRAF/BET inhibition, we performed RNA sequencing followed by gene set enrichment analysis (GSEA) of drug‐treated tumors." (PMID 27169980, 2016). "The median age at detection of brain metastasis was 56.0 years in BRAF mutated tumours, 59.5 years in NRAS mutated tumours and 69.5 years in BRAF wild-type tumours." (PMID 27213536, 2016). "In vitro data would suggest that during the acquisition of BRAF-i resistance, tumor cells develop cross-resistance to NK-mediated lysis." (PMID 27563819, 2016). "These include gain-of-function mutations in EGFR, K-RAS, BRAF, and EML4-ALK, all signifying the importance of the MAPK pathway for this tumour type." (PMID 27350784, 2016). "Clonal proliferation has been reported with the presence of BRAF V600E oncogenic mutation in more than half of patients with LCH, which suggests a neoplasm." (PMID 26749317, 2016). "BRAF mutation is very rare in patients with NSCLC, and its presence is associated with sensitivity of tumor cells to BRAF inhibitors (vemurafenib, dabrafenib)." (PMID 25902737, 2016). "For nine patients in the cohort, mutational analyses for KRAS, BRAF, and PIK3CA hotspots were available for matched tumor tissue, CTCs, and ctDNA." (PMID 27863403, 2016). "BRAF-directed therapy initially decreases tumor burden considerably; however, most patients ultimately develop resistance and tumors recur." (PMID 27583134, 2016). "Mutations in KRAS, NRAS, BRAF, and PIK3CA genes were evaluated for association with several pathological parameters: sex, age at diagnosis, anatomical location of primary CRC, tumour grading, AJCC stage of the disease." (PMID 27737711, 2016). "For single gene or tumor phenotype biomarker, microsatellite instability (MSI) high is a validated prognostic biomarker in early stage colorectal cancer while the prognostic value of BRAF or KRAS mutation depends on microsatellite status and tumor location." (PMID 27623752, 2016). "Additional understanding of the immune-modulatory effects of BRAF as well as MEK inhibition in the tumor microenvironment is warranted." (PMID 27532019, 2016).
tumor (continued). "Genomic DNA was isolated from formalin-fixed, paraffin-embedded primary tumour tissue samples of CRC patients and screened for mutations in RAS and BRAF genes, using pyrosequencing assays, and in PIK3CA gene, using automated DNA sequencing assays." (PMID 27737711, 2016). "In the multivariate analysis, we selected sex, age, tumor differentiation, nodal stage, KRAS, BRAF and PIK3CA gene mutations in relation to DFS and OS by stage and in both stages combined together." (PMID 27074743, 2016). "Taken together these data suggest that cells with mutational activation of BRAF, require TGFBR1 for efficient colony formation and that TGFβ would predictably function as a tumour promoter." (PMID 27835901, 2016). "It is now accepted that in stage IV colorectal disease, RAS mutations confer resistance to anti‐EGFR therapy and BRAF mutations are an indicator of poor prognosis; however, even among patients with RAS WT tumours, only a minority respond." (PMID 26690310, 2016). "The results show consistently favourable efficacy for first-line panitumumab + FOLFIRI treatment in patients with RAS WT/BRAF WT tumours compared with MT mCRC tumours." (PMID 27764839, 2016). "First-line panitumumab+FOLFIRI was associated with favourable efficacy in patients with RAS WT and RAS WT/BRAF WT vs MT mCRC tumours and was well tolerated." (PMID 27764839, 2016). "Animal studies have shown that host immunity can contribute to the anti-tumour activity of BRAF inhibition, with CCR2 suggested as an important participant." (PMID 26857260, 2016). "Melanoma tumor containing the BRAF V600E mutation are resistant to EGFR inhibitors, and treatment with BRAF inhibitors demonstrates remarkable effects on the tumor." (PMID 27094161, 2016). "Those patients who develop the most slowly but continued response to these BRAF inhibitors appear to achieve a more sustained response when compared with those patients who develop a very rapid tumour clearance." (PMID 27841141, 2016). "PCR-based sequencing for hot spot mutations of KRAS, BRAF and PIK3CA genes in CTCs revealed similar mutations as tumor biopsies for 77.8% of the patient samples." (PMID 27863403, 2016). "Somatic mutations in these genes were detected in 537 of 1284 (41.8 %) primary tumours: 457 (35.6 %) KRAS, 53 (4.1 %) NRAS, and 27 (2.1 %) BRAF mutations." (PMID 27737711, 2016). "BRAF mutations can result in increased or decreased BRAF kinase activity, as well as kinase-neutral mutations, and BRAF mutations occur in 3–8% of patients with NSCLC and many other tumor types." (PMID 26623721, 2016). "Other studies showed that BRAF inhibition resulted in an improved infiltration of adoptively-transferred T cells in vivo, thus enhancing the anti-tumor activity of adoptive cell transfer (ACT) therapy." (PMID 27563819, 2016). "How the initial switch from tumour suppressor to tumour promoter function of TGFβ in melanocytes is mediated by mutant BRAF remains to be determined." (PMID 27835901, 2016). "Prior to these studies, we knew, for example, that BRAF and NRAS mutations occurred but tumour sequencing studies have helped us to resolve their absolute prevalence, particularly at positions outside of the canonical BRAFV600 and NRASQ61 residues." (PMID 26354726, 2016). "As observed by others and similarly to BRAF mutations, MSI tumours were found to have larger tumour size, association with lower disease stage and poor differentiation." (PMID 25884297, 2015). "In our study we have used the TCGA dataset to identify the changes that are seen in methylation in BRAF mutant tumours." (PMID 26097884, 2015). "Tumor cells in which the BRAF pathway is constitutively active, due to the presence of mutant BRAF, generally have a high rate of proliferation." (PMID 26029997, 2015).
tumor (continued). "In the context of EMT-driven cellular plasticity, it is important to note that clinically CIMP-low/MSS/MSI-low/BRAF mutant tumors confer a poor prognosis and display high tumor budding." (PMID 25699236, 2015). "The BRAF mutant cancers had an older age of onset, a propensity to affect females, a frequent proximal tumour location, an earlier stage at presentation and a mucinous histology compared to BRAF wild type cancers." (PMID 25613750, 2015). "Characterization of mutant proteins has revealed a mutation hotspot resulting in a valine to glutamate substitution at position 600, often referred to as BRAF V600E in a range of tumor types." (PMID 25785246, 2015). "C57BL/6 mice with established subcutaneous SM1 tumors were treated with the CSF-1R inhibitor PLX3397 and the BRAF inhibitor PLX4032 daily once tumor diameter reached ~5 mm." (PMID 25939769, 2015). "Among the 302 tumours examined for gene mutations, KRAS mutations were found in 40.7% and BRAF mutations in 4.9%." (PMID 25970543, 2015). "It is worth noting here that TRAP1 upregulation protected scramble and shTRAP1 cells from irinotecan-induced apoptosis, whereas its cytoprotective activity was lost in tumor cell lines silenced for BRAF." (PMID 26084290, 2015). "In PDA tumours harbouring wild-type KRAS, we identified BRAF and PIK3CA mutations at oncogenic hotspots expanding the spectrum of oncogenic drivers in PDA." (PMID 25855536, 2015). "We focused on PTC, as the BRAF V600E mutation is a frequent genetic alteration in PTC, with frequencies of up to 73%, and as previous studies had indicated a potential tumor suppressor function of MIG-6 in this disease." (PMID 26065894, 2015). "Mechanistically, a feedback activation of EGFR was identified upon BRAF inhibition in BRAFm CRC supporting persistent tumor cell proliferation through reactivation of the MAPK and PI3K pathways." (PMID 26617477, 2015). "From January 2010 to August 2013, 1797 FFPE tumor samples, derived from patients with mCRC, mMEL and NSCLC were selected to detect K-RAS, BRAF and EGFR somatic mutations, respectively." (PMID 25844806, 2015). "In an analysis of 91 tumours (9 BRAF mutant, 82 wild type), the Illumina probe cg11835197 was the probe identified as top differentially methylated (p = 2.56×10-7, Bayes Factor (BF) =6.54)." (PMID 26097884, 2015). "By comparison, Erastin has been reported to exhibit greater lethality in human tumor cells harboring mutations in the oncogenes HRAS, KRAS, or BRAF as well as in an individual genetic context using isogenic cell lines with and without oncogenic RAS genes." (PMID 26157704, 2015). "In a multiple logistic regression model with the variables CNV, CIMP, MSI, KRAS, BRAF, stage, tumor localization and gender, the only variable that was retained in the model for recurrence risk was stage." (PMID 25879218, 2015). "When the MEK inhibitor AZD6244 was tested against PA xenograft models, complete regression was observed in the BRAF V600E mutant xenograft whereas tumor progression was observed in wild-type BRAF xenografts." (PMID 25785246, 2015). "Conversely, subjects both with tumours < = 10 mm in diameter and microcarcinoma (unifocal pT1a) were over-represented among BRAF(-) population: in BRAF(-) tumours there were 47 patients with tumour size to 10 mm (49.5%) vs 39 among BRAF(+) (30.7%, p = 0.03)." (PMID 26177218, 2015). "Intriguingly however, both BRAF-KRAS double-mutant tumours had reported micropapillary architecture (compared to 5/55 cases of remaining cohort, p = 0.01, FET)." (PMID 26506417, 2015).